TLR4 (toll like receptor 4)
Diseases named in the same sentence as TLR4 in open-access papers (continued):
Sharing a sentence is not in itself a finding about the gene and the disease.
tumor (continued). "Moreover, we have emphasized the importance of a new paradigm which can promote the anti-tumor effects of MSCs via stimulation of TLR4." (PMID 31857958, 2019). "Finally it was shown by us that TLR4 expressed on tumor cells is the agent promoting growth and preventing cells from cell-mediated immunity in head and neck squamous cell carcinoma." (PMID 30976817, 2019). "Thus, TLR4 is required for the effective induction of T-cell dependent anticancer immunity in this genetic lung cancer tumor model following treatment with chemotherapy." (PMID 31191545, 2019). "We investigated the immune modulatory properties of TEX released upon cell TLR4 activation, and we found that, although differences were observed depending on the type of the tumor, the treatment influences TEX composition and boosts their immunosuppressive ability." (PMID 31186484, 2019). "LPS could activate TLR4 signaling in tumor cells and help tumor cells escape attack from cytotoxic lymphocyte (CTL) and natural killer (NK) cells." (PMID 32010645, 2019). "Furthermore, xenograft tumour differentiation was poorer in TLR4 group than in GFP ctrl group, whereas that was better in TLR4i group than in RNAi ctrl group (upper pictures)." (PMID 29602239, 2018). "PAUF (A) and TLR4 (B) expression increased during tumor progression." (PMID 30111860, 2018). "Modification with folate has been reported to overcome TLR4 driven chemotherapy resistance, and its co-encapsulation of anti-tumor agents could be a promising option." (PMID 30143890, 2018). "Furthermore, tumor-induced elevation of circulating pro-inflammatory cytokines was similarly abolished in both genetic ablation and pharmacological inhibition of TLR4." (PMID 30575787, 2018). "Recent research revealed an association between TLR4 expression and tumor aggressiveness and a poor prognosis for patients with HCC, although the mechanisms by which TLR4 promotes cancer progression are still unknown." (PMID 29338742, 2018). "TLR4 has been observed as over-expressed in human and mouse colorectal neoplasia, and on the other hand, TLR4-deficient mice are refractory to colon carcinogenesis, indicating that the higher TLR presence on tumor cells induces tumor development directly or indirectly by mean of angiogenesis." (PMID 29649166, 2018). "Our data demonstrated that PAUF and TLR4 expression were increased from benign to advanced tumor, and their correlation coefficient was increased in advanced stages (stage III/IV) and grade 3 compared to early stages (stage I/II) and grade 1/2 cancer specimens." (PMID 30111860, 2018). "In addition to inducing p65 nucleus translocation, LPS has also been reported to activate TLR4 signaling, which is also an essential pathway in the pathopoiesis of tumors; interestingly, TLR4/NF-κB signaling mediates diverse tumor growth." (PMID 29788922, 2018). "Also, the expression of TLR-4 on tumor cells was reported to play a role in immune surveillance and facilitate tumor growth and chemoresistance." (PMID 30680070, 2018). "Similarly, high expression of TLR4 correlated with advanced tumor stage (p = 0.002) and chemoresistant tumor (p = 0.001)." (PMID 30111860, 2018). "However, this action can be fully abrogated by depletion of HP1α, HP1β and HP1γ, and (v) TLR4 overexpression leads to increase in cell proliferation, colony formation and xenograft tumour formation ability." (PMID 29602239, 2018). "Toll-like receptor 4 (TLR4) is a molecular biomarker of tumor aggressiveness and poor prognosis." (PMID 29338742, 2018). "The role of TLR4 in tumor progression has been described in many studies." (PMID 30213077, 2018). "Moreover, TLR4 signaling triggered by HMGB1 is able to stimulate an inflammatory response leading to tumor development in a skin model of tumorigenesis." (PMID 29472602, 2018). "Specifically, increased TLR4 expression in MCL cells can contribute to tumor progression." (PMID 29907126, 2018).
tumor (continued). "Once secreted, HMGB1 binds dendritic cell Toll-Like Receptor 4 on its surface, leading to an effective anti-tumor immune response that may eliminate tumor cells, preventing the spread of metastasis." (PMID 29783720, 2018). "In humans, the IT delivery of the synthetic TLR4 agonist Glucopyranosyl Lipid A (G100) has showed success in early clinical trials in eliciting Th1 polarized anti-tumor immunity in Merkel cell carcinoma and soft tissue sarcoma, in combination with RT (NCT02501473)." (PMID 30619273, 2018). "The use of a TLR4-deficient mouse tumor model, as well as in vitro experiments in which the S100A4 receptor was blocked in MDSCs, finally established that the activation of TLR4–ERK signaling by extracellular S100A4 is responsible for the resistance of MDSCs to intrinsic apoptosis induction." (PMID 29556233, 2018). "The role of TLR4 should be further examined in the different tumor types." (PMID 30213077, 2018). "This was in concordance to the findings herein that IL-8 was significantly increased in both TLR4-positive and TLR4-deficient BCA cells when exposed to PTX so that IL-8 might be a predictive marker for tumor-promoting aggressiveness in BCA." (PMID 29486738, 2018). "TLR-4 is the first identified member of the TLRs family expressed in many type of tumors and accumulating evidences demonstrated that the activation of TLR-4 in tumor microenvironment can not only boost the anti-tumor immunity but also give rise to immune surveillance and tumor progression." (PMID 30680070, 2018). "Such TLR4 positivity conferred a proliferative phenotype to these tumor cells." (PMID 29912993, 2018). "In addition, the xenograft tumours appeared earlier in TLR4 group than in GFP ctrl group (P < .05), whereas those appeared later in TLR4i group than in RNAi ctrl group (P < .01)." (PMID 29602239, 2018). "TLR4 was the most expressed receptor in both cell lineages and tumor specimens." (PMID 29912993, 2018). "By contrast, in the lung microenviroment the decreased TLR4/NLRP3 axis could represent a tumor mediated immunosuppression." (PMID 30365491, 2018). "TLR4 is expressed in a number of tumor cell lines, including 4T1 and MDA-MB-231, as well as LECs." (PMID 29976154, 2018). "Therefore, it was important to investigate the potential of our model and the inoculated tumor cells to induce the expression of TLR4 and to initiate an innate immunity response." (PMID 29637027, 2018). "In mice with hepatocyte-deletion of Pten, TLR4 but not TLR2 deficiency suppressed tumor growth as well as hepatic inflammation, in good agreement with the results of our study." (PMID 30034633, 2018). "Notably, overexpression of PAUF and TLR4 correlated with aggressive tumor phenotypes, including chemoresistance." (PMID 30111860, 2018). "Therefore, this review focused on the expression and function of TLR4 on DCs, TAMs, T cells, MDSCs, tumor cells and stromal cells in tumor microenvironment." (PMID 29029545, 2017). "Thus, we conclude that tumor cell-released extracellular Hsp70 and Hsp90 induce muscle wasting by activating TLR4-mediated muscle catabolism." (PMID 28928431, 2017). "In addition, we demonstrate that tumor-released Hsp70 and Hsp90 induce muscle wasting by activating TLR4 on muscle cells." (PMID 28928431, 2017). "Alcohol may initially activate EGFR/ErbB2 and/or induce ROS, which stimulate critical signaling components, such as p38 MAPK, Wnt/GSK3β/β-catenin, and TLR4/Nanog, as well as alter tumor microenvironment, resulting in the promotion of CSCs." (PMID 29156633, 2017). "Indeed, a previous study found that TLR4 was involved in the formation of intestinal inflammatory-related tumor microenvironment." (PMID 28626766, 2017). "LPS-activated TLR4 signaling renders tumor cells resistant to CTL-induced killing, which might be attributed to increased expression of B7-H1, B7-H2, and CD40 and decreased expression of Fas." (PMID 28881826, 2017).
tumor (continued). "In addition to endogenous ligands secreted by necrotic tumor cells, TLR4 is also directly activated by paclitaxel, a chemotherapeutic drug against various human cancers." (PMID 29029545, 2017). "Interestingly, the similar effect of TLR4 on angiogenesis is also discovered in tumor microenvironment." (PMID 29029545, 2017). "Tumor-derived sCRT39-272 should be able to help sustaining such an inflammatory microenvironment because of its potent ability to elicit proinflammatory cytokine production by monocytes/macrophages via CD14/TLR4 as documented by our previous work." (PMID 29075268, 2017). "TLR4-induced HIF-1α may be involved in tumor immune escape as well, providing a new concept for the further analysis of HPV pathogenesis." (PMID 29263932, 2017). "Our study explored the often stated hypothesis that BMTT using gram-negative bacteria can be reduced to a mere adjuvant effect stimulating an anti-tumor immune response exclusively along the LPS/ TLR4 axis." (PMID 28445131, 2017). "Finally, we demonstrate that stimulation of the TLR4 pathway in vitro can increase the sensitivity of tumor cells to the chemotherapy agent docetaxel, thus identifying a possible approach to increase the efficacy of this drug in docetaxel-resistant disease." (PMID 28915246, 2017). "A possible mechanism is that defective TLR4 signaling may negatively impact epithelial cell repair, which is in part dependent on TLR4 stimulation, and potentially enable microbes to breach the epithelial barrier in the tumor microenvironment." (PMID 28531216, 2017). "In addition to that, our results revealed that the tumor delay of TLR4 overexpressing tumors correlated with the lower expression of ki67 proliferation marker." (PMID 28982115, 2017). "Considering the role of CD4 CTLs in controlling HIV, malaria, and other infections, it is intriguing to speculate about the activity of CD4 CTLs in tumor environment after TLR4 agonist adjuvant." (PMID 29029545, 2017). "Furthermore, TLR4 activation on tumor cells can prevent their lysis, thereby protecting cancer cells." (PMID 29354132, 2017). "The correlation between CDSE1 and TLR4, TLR7 or TLR8 expression suggests that PDAC patients with high UNR/CDSE1 expression may present a less aggressive tumor phenotype, more susceptible to be cleared by the immune response." (PMID 28763470, 2017). "In addition, TLR4 activation can promote tumor growth and resistance to chemotherapy and mediate the immune escape of epithelial ovarian cancer cells." (PMID 28626766, 2017). "Furthermore, activation of TLR4 on T cells have anticancer and pro-tumor consequence in tumor microenvironment." (PMID 29029545, 2017). "This control tumor served as a basis for comparison of the TLR4 expression level." (PMID 28982115, 2017). "Besides, the mRNA and protein expressions of TLR4, TRAF-6, NF-κB and AP-1 in the splenocytes of the TLR4+/+ EAC tumor-bearing mice were also observed increased significantly." (PMID 28303957, 2017). "In aggregate, activation of TLR4 on T cells by ligands in tumor microenvironment might have both anticancer and pro-tumor consequences through multiple mechanisms." (PMID 29029545, 2017). "The pathogen recognition receptor TLR4 is undoubtedly involved in the induction of inflammatory cytokines and is expressed in a variety of cell types, most notably immune cells and also tumor cells as our data illustrates." (PMID 28915246, 2017). "The differences in the Ki67 expression level between TLR4 overexpressing tumors and control tumors were presented as [%] positive cells in the tumor area Ki67 positive cells were counted out of all cells in the whole section of TLR4 overexpressing and control tumors." (PMID 28982115, 2017). "It was therefore of interest to determine whether inhibition of TLR4 signaling with either penta-acylated LPS from R. Sphaeroides (LPS-RS) or TAK-242 would inhibit docetaxel-induced TNF-α release in tumor cells." (PMID 28915246, 2017).
tumor (continued). "Immunostaining demonstrated TLR4 and 8 significantly correlated in tumor tissue, similar to RNA." (PMID 29190881, 2017). "Additionally, quantitative RT-PCR was performed in 22 tumor samples with available RNA (11 of which contained TLR pathway mutations, including 5 TLR4 mutations)." (PMID 28531216, 2017). "In addition, curdlan has been reported to activate DCs through Dectin-1 and TLR4 signaling and the combination of curdlan and DCs efficiently inhibit tumor growth in mice." (PMID 29163499, 2017). "HMGB1 has also been shown to have a role in tumour metastasis in a mechanism involving TLR4." (PMID 29170605, 2017). "Although TLR4 activation on tumor cells, stroma cells as well as vascular epithelial cells definitely benefits the tumor, stimulation of this pathway in immune cells may have two reversal consequences." (PMID 29029545, 2017). "TLR4 was reported to promote tumor growth, metastasis, and immune escape in many tumor cells." (PMID 29228698, 2017). "Therefore, TLR4 takes an important part in facilitating the formation of vessels in tumor microenvironment through multiple mechanisms." (PMID 29029545, 2017). "However, TLR4 activation on tumor or on stromal cells promotes immune surveillance and tumor progression." (PMID 29029545, 2017). "Validation of the multiple role of TLR4 in tumors could primarily pave the road for the development of anti-tumor immunotherapy." (PMID 29029545, 2017). "TLR4 expresses not only on immune cells but also on tumor cells." (PMID 29029545, 2017). "This supports our data concerning TLR4 expression and keratinocytes proliferation and tumor growth." (PMID 28982115, 2017). "Consequently, muscle fibers in tumor-bearing TLR4−/− mice maintained normal histology and mass as measured by cross sectional area in contrast to tumor-bearing wild-type mice in which muscle fibers shrank and interstitial space increased." (PMID 28536426, 2017). "TLR4 is over expressed in malignant tumors and tumor-infiltrating immune cells." (PMID 27273624, 2016). "If inflammation facilitates tumor progression through the induction of more suppressive MDSCby signaling through the toll-like receptor 4 (TLR4) pathway, then it is possible that a decreased pro-inflammatory microenvironment may reduce the potency of MDSC." (PMID 27649234, 2016). "Thus, histones promote tumor metastasis of HCC cells through the TLR4-NF-κB pathway and represent novel targets for treating patients with HCC." (PMID 27623211, 2016). "In support of this view, the tumour cells utilized in this study expressed TLR2 and TLR4, and neutralizing antibodies against these receptors indeed inhibited tumour cell migration toward biglycan, which suggested a common mechanism for biglycan to activate cell migration." (PMID 27295191, 2016). "TLR4 is a transmembrane receptor that is overexpressed in tumor cells." (PMID 27242527, 2016). "Results showed that TLR4 and miR-21 expressions were significantly higher in tumor tissues." (PMID 27286259, 2016). "Immunomodulating drugs targeting TLR4 are actively investigated in cancer, where TLR4 persistent activation can induce chronic inflammatory conditions contributing to carcinogenesis, while TLR4 agonists can induce anti-tumor immunity." (PMID 27909407, 2016). "Biglycan-treated tumour cells showed significant increases in NF-κB activity, whereas this induction was attenuated by pretreatment with TLR2 and/or TLR4 inhibitors, suggesting that biglycan-induced tumour cell migration was mediated by NF-κB activation through TLRs." (PMID 27295191, 2016). "Activation of TLR4 on immune cells can enhance anti-tumor immunity." (PMID 26883191, 2016). "TLR4 activation may trigger local and systemic inflammation, creating a regenerative tumor microenvironment favoring local recurrence and metastasis." (PMID 27273624, 2016).
tumor (continued). "Expression of TLR4 and its signaling of tumor cells have been demonstrated to induce the synthesis of soluble immune mediators that could help the tumor to invade the immune attack." (PMID 26883191, 2016). "Moreover, HMGB1 and HSP70/90 from immunogenic tumor cells interact with TLR4 on DCs, which activates the antigen processing and presentation machinery in DCs." (PMID 27240347, 2016). "Human EOC cells usurp or hijack TLR4/MyD88 signaling pathway that considerably activates NF-κB and Akt pathways, which trigger expression of immunosuppressive molecules resulting in immune incompetence in the tumor microenvironment." (PMID 27118139, 2016). "Indeed, we recently uncovered a specific interaction between dying and remnant live cells through a specific HMGB1/TLR4-RAGE pathway that induces sCLU in the live cells to develop chemoresistance in tumor cells." (PMID 27405665, 2016). "Moreover, TLR4 has been reported to induce Th1 responses in studies of immune adjuvants for tumor-therapy." (PMID 26891999, 2016). "Interestingly, priming of tumor induced macrophages with TLR4 agonist (LPS) alone or in combination with IFN-γ not only altered M2 polarization but also induced a strong anti-tumor immune reaction." (PMID 27511884, 2016). "Some research showed that activation of TLR4 and NF-κB increased some chemokines expression, which induced cell apoptosis, inhibited tumor proliferation, and reduced tumor progression, resulting in a durability and effectiveness of anti-tumor immune response." (PMID 26760960, 2016). "Activation of the TLR4 signalling pathway in tumour cells is a “double-edged sword”51." (PMID 27090571, 2016). "However, in contrast to findings implicating a role of TLR4 in tumor progression our data rather indicate that TLR4 signaling potently induced apoptosis in M13MDA435 hybrid cells via different mechanisms." (PMID 26863029, 2016). "Our biochemical studies revealed a physical interaction between TLR4 and HBx in HepG2.2.15 cells, which may account for the tumor-promoting effects of TLR4 in HBV-related HCC cells." (PMID 26514586, 2015). "Interestingly, alongside hepatocytes, HSC were identified as candidates for TLR4-dependent tumour promotion in the chronically injured liver." (PMID 26013123, 2015). "Furthermore, in B10 (TLR4+/+) tumor-bearing mice, the thymus index in the ADM group decreased significantly, as compared with that in the saline group (p < 0.05)." (PMID 26032186, 2015). "Additionally, it has been reported that TLR4 expression by DC is a prerequisite for efficient antigen presentation of tumor antigens provided by dying cancer cells." (PMID 25973756, 2015). "In vivo studies confirmed the mediating role of TLR4 in HBV-related HCC tumor growth." (PMID 26514586, 2015). "However, combining DC mobilization with TLR4-triggering was efficacious for the treatment of different murine tumor models." (PMID 25682197, 2015). "Additionally, LPS activation of TLR4/MyD88 signaling has been shown to play an important role in pancreatic cancer tumor growth and migration, and blockade of this pathway decreases tumor invasive ability." (PMID 26172047, 2015). "The therapeutic effect is probably due to the direct impact of BLS on tumor cells TLR4." (PMID 25973756, 2015). "Finally, we have shown that BLS impacts on B16 cells via TLR4 generating a subsequent diminished tumor growth." (PMID 25973756, 2015). "Indeed, it has been shown that HMGB1 released by dying tumor cells activates DC via TLR4 enhancing the efficacy of anti-tumor CTL responses." (PMID 26075613, 2015). "Twenty five days after administration, TLR4, TRAF6, NF-κB and AP-1 in PSP and LPS group (positive control) were significantly increased at mRNA and protein level relative to those of the saline group in the spleen of B10 (TLR4+/+) tumor-bearing mice (all p < 0.05)." (PMID 26032186, 2015).